MAGEB4 (MAGE family member B4)
Synonyms: MGC33144; CT3.6
Tractability: PROTAC: ubiquitination databases record sites on it.
Gene: Protein-coding gene on chromosome X (30,242,000 to 30,244,187, forward strand). Ensembl gene ENSG00000120289.
Subcellular location: Cytoplasm
Gene Ontology:
Molecular function: protein binding
Biological process: negative regulation of transcription by RNA polymerase II
Cellular component: nucleus; cytoplasm
Homologues: Orthologues: chimpanzee MAGEB4 (99% identical), zebrafish ndnl2 (24% identical), Drosophila melanogaster MAGE (18% identical). Paralogues in human: MAGEB1 (68% identical), MAGEB2 (60% identical), MAGEB3 (54% identical), MAGEB17 (54% identical), MAGEB10 (51% identical), MAGEB18 (51% identical), MAGEB6 (48% identical), MAGEA10 (47% identical), MAGEB6B (47% identical), MAGEB16 (44% identical), MAGEA11 (41% identical), MAGEB5 (40% identical), and 25 more.
Diseases named in the same sentence as MAGEB4 in open-access papers:
MAGEB4 is named in the same sentence as 10 diseases in open-access papers, as found by Europe PMC text mining. Sharing a sentence is not in itself a finding about the gene and the disease. The quoted sentences say what the papers report.
Azoospermia (1 paper, 2021). Absence of any measurable level of sperm,whereby spermatozoa cannot be observed even after centrifugation of the semen pellet. "Among the five patients we used as controls, there were 2 non-obstructive azoospermia patients; C1 had a hemizygous stop-loss in MAGEB4 and C2 had a homozygous stop-gain in TEX15." (PMID 33809228, 2021).
breast carcinoma (1 paper, 2020). "Although their expression is not yet well investigated in PDAC, a recent study showed that high expression levels of MAGEB4 mRNA in breast cancer patients correlate with an improved relapse-free survival, regardless of breast cancer subtype." (PMID 33266496, 2020).
chronic lymphocytic leukemia (1 paper, 2022). "MNDA and MAGEB4 (- methylation) are myeloid cell differentiation antigen involved in chronic lymphocytic leukemia and other cancers and cancer-testis antigens associated with immunotherapy treatment responses and undergoing aberrant methylation." (PMID 36812605, 2022).
serous ovarian cancer (1 paper, 2021). "In the serous ovarian cancer patients of cohort 2 (n = 20/80), detectable antibodies (Z-scores > 0) were seen against CTAG2 (n = 3/20, 15%), SHARPIN (n = 2/20, 10%), PNMA2 (n = 2/20, 10%), MAGEB4 (n = 1/20, 5%), MRFAP1L1 (n = 1/20, 5%), SERPINB1 (n = 1/20, 5%) and XAGE3 (n = 1/20, 5%)." (PMID 34681879, 2021).
MAGEB4 also shares sentences with these, for which no sentence is quoted: cancer (4 papers); colon cancer (1); melanoma (1); ovarian carcinoma (1); transitional cell carcinoma (1); tumor (1).